ERBB3 (erb-b2 receptor tyrosine kinase 3)
Diseases named in the same sentence as ERBB3 in open-access papers (continued):
Sharing a sentence is not in itself a finding about the gene and the disease.
breast cancer (continued). "We found that TF expression in breast cancer lines and tumors closely clustered with higher levels of EMT (high vimentin/low E-cadherin) and classical basal-type biomarkers KRT5, KRT14 and caveolin-1, while it clustered with lower levels luminal-type biomarkers KRT8, KRT18, ERBB3 and ESR1." (PMID 28938620, 2017). "Collectively, our studies demonstrate that erbB3 receptor and IGF-1R differentially modulate lapatinib sensitivity in trastuzumab-resistant breast cancer cells; and specific knockdown of erbB3, but not IGF-1R, significantly promotes lapatinib-mediated growth inhibition and apoptosis." (PMID 26621843, 2016). "Because the targeting of ERBB3 has the potential to enhance the efficacy of other RTK inhibitors, combinatory treatments with both miR-143/145 and ErbB-targeted drugs may offer a viable strategy for breast cancer therapy." (PMID 25248370, 2014). "Nonetheless, the precise mechanism by which erbB3 signaling specifically upregulates Survivin, but not the functionally related molecules Mcl-1 and Bcl-xL in erbB2+ breast cancer cells remains unknown." (PMID 24886126, 2014). "We previously reported that the three RTKs, erbB2, erbB3, and IGF-1R interacted with each other to form a heterotrimeric complex, which activates the downstream signaling, such as PI-3 K/Akt or MEK/MAPK pathways and Src kinase in trastuzumab-resistant breast cancer cells." (PMID 24168763, 2013). "However, the mechanism of HRG-β1 and ErbB3 for the regulation of EMT in breast cancer cells has not been documented in detail." (PMID 23937725, 2013). "In addition, we have found that hMP-RM-1, a humanized version of the anti-erbB3 Ab MP-RM-1, exhibited similar in vitro activity to specifically downregulate Survivin in erbB2-overexpressing breast cancer cells (data not shown)." (PMID 24168763, 2013). "Hence, therapeutic targeting of ErbB3 in combination with HER2 may be the most appropriate strategy to achieve full efficacy of anti-HER2 targeted therapy, in particular for breast cancer." (PMID 22889873, 2012). "Interestingly, over-expression of miR-125a did not significantly repress the expression of ERBB2 or ERBB3, which were demonstrated to be critical for inhibiting the proliferation and metastasis of breast cancer." (PMID 22768249, 2012). "Interestingly, erbB3 also possesses the NPXY motifs recognized by IRS proteins and as such may bind IRS-1 in breast cancer cells." (PMID 21939528, 2011). "Since we have previously demonstrated that β4 depletion reduces the responsiveness of mammary tumor cells to TAM treatment, our data also suggest that a cooperative signaling between ErbB-3 and α6β4 integrin could influence resistance to hormone therapy in vivo." (PMID 18270579, 2008). "The results we obtained on cell death and apoptosis on T47D cells strongly reinforce our hypothesis that ErbB-3 sustains the survival function of mammary tumor cells in the absence of hormone stimuli." (PMID 18270579, 2008). "The ErbB family (ErbB1/EGFR, ErbB2/HER2, ErbB3/HER3 and ErbB4/HER4) of receptor tyrosine kinases (RTKs) is known to drive both formation and progression of a number of commonly occurring cancers, including breast cancer, due to the normal role of these RTKs in regulating cell growth and survival." (PMID 18841159, 2008). "Furthermore, blocking ER using antisense strategies resulted in increased ErbB1, no change in ErbB2 and a slight decrease in ErbB3 expression in breast cancer cells." (PMID 16519802, 2006). "We noted enhanced phosphorylated Akt and MAPK in a perivascular distribution in mammary tumors, with overexpression of both erbB2 and erbB3, suggesting that circulating HRG may enhance the physical and functional erbB2/erbB3 interactions in vivo, similar to what we observe in vitro." (PMID 16168116, 2005).
breast cancer (continued). "Data from part A of the TOT-HER3 trial revealed that HER3-DXd is associated with clinical response, increased immune infiltration, and proliferation suppression with an acceptable safety profile in patients with HR+/HER2-negative early breast cancer, regardless of baseline ERBB3 levels." (PMID 38894701, 2024). "In human epidermal growth factor receptor 2‐positive breast cancer cell lines, free tRNALeu may interact with human epidermal growth factor receptor 3 (ErbB3) and binding protein (EBP1), which in turn activates the ErbB2/ErbB3 signaling pathways, and ultimately promotes cancer cell proliferation." (PMID 34048096, 2021). "We have also investigated whether the newly identified miRNA-based strategy, targeting of erbB3 with two functional cooperative miRNAs, can significantly enhance the anti-proliferative/anti-survival effects of trastuzumab and paclitaxel on HER2-overexpressing breast cancer cells." (PMID 30093840, 2018). "It is not clear whether a novel strategy with two functional cooperative miRNAs would effectively inhibit erbB3 expression and potentiate the anti-proliferative/anti-survival effects of a HER2-targeted therapy (trastuzumab) and chemotherapy (paclitaxel) on HER2-overexpressing breast cancer cells." (PMID 30093840, 2018). "However, it remains unclear whether erbB3- and IGF-1R-initiated signaling pathways possess distinct effects on the sensitivity of lapatinib, a dual tyrosine kinase inhibitor against both EGFR and erbB2, in trastuzumab-resistant breast cancer." (PMID 26621843, 2016). "Similarly, it has been demonstrated that the down-regulation of ErbB3 expression, and of its downstream pathways, by the HDACi SNDX-275, is a crucial mechanism to overcome the resistance to the anti-ErbB2 antibody trastuzumab in an ErbB2-overexpressing breast cancer model." (PMID 26862736, 2016). "Thus, ERBB3 was determined to be a miR-143/145 target, based on both computational predictions and the inverse correlation between miR-143/145 levels and ERBB3 protein levels, but not mRNA levels, in human breast cancer." (PMID 25248370, 2014). "In the present study we have, for the first time, examined whether HRGs can similarly promote erbB3/PI3K/AKT signalling and effectively circumvent the inhibitory effects of the anti-EGFR agent gefitinib on the growth and invasion of an EGFR-positive Tam-R breast cancer cell line." (PMID 17686159, 2007). "For breast carcinomas, it was shown that neuregulin 1 (ligand for ERBB3 and ERBB4 tyrosine kinase receptors), but not Wnt3A, is indispensable for the isolation and long-term culture and expansion of breast cancer PDOs." (PMID 40863456, 2025). "Patritumab deruxtecan (HER3-DXd) exhibits promising efficacy in breast cancer, with its activity not directly correlated to baseline ERBB3/HER3 levels." (PMID 38992028, 2024). "The endogenous p95 ErbB2 in BT474 breast cancer cells does not respond to EGF as the full-length ErbB2, but instead gets phosphorylated and activated in response to ErbB3 and ErbB4 ligand heregulin." (PMID 24709902, 2014). "In ERα negative breast cancer, ERBB2 overexpression significantly correlates with high AR and ERBB3 expression." (PMID 23593223, 2013). "In MDA-MB-453 breast cancer cells that do not express ERα, AR activates ERBB2 signaling by direct androgen-dependent induction of WNT7B and ERBB3 expression." (PMID 23593223, 2013). "Similar to human ERBB2 driven breast cancer, tumors in ERBB2 transgenic animals show simultaneous increase in endogenous ERBB3 but not ERBB4 expression." (PMID 23593223, 2013). "Consistent with such a mechanism is the fact that both pertuzumab, which inhibits ErbB2/ErbB3 heterodimerization and signalling, and ALM are active preclinically against breast cancer cells that are not gene-amplified for ErbB2." (PMID 18841159, 2008).
breast cancer (continued). "However, unlike breast cancer cells, this was independent of NRG1-ERBB3 signaling because co-treatment with INK128 combined with ERBB3 inhibitor MM-121 also showed increased pAkt T308, similar to INK128 alone." (PMID 33273014, 2021). "This signaling is ERBB2-specific and appears not to depend on ERBB2 heterodimers as in the context of the breast cancer cell line used here (expressing negligible ERBB4 levels), silencing of EGFR and ERBB3 does not impair the ERK-dependent AKT de-phosphorylation elicited by Abs." (PMID 33037285, 2020). "Gene clusters correlating positively (including known GRHL2 targets such as ErbB3, CLDN4/7) or negatively (including TGFB1 and TGFBR2) with GRHL2 in the MCF7 knockout model, display similar correlation with GRHL2 in ER positive as well as ER negative breast cancer patients." (PMID 36691073, 2023).
lung cancer (155 papers, 2006 to 2026). A malignant neoplasm involving the lung. "Somatic alterations with ErbB3 gene were identified in the tissue of lung cancer associated with IPF." (PMID 37800117, 2023). "We then repeated the validation analysis with other two target genes, HIF1A and ERBB3, both of which have expressions associated with lung cancer progress and prognosis." (PMID 34422018, 2021). "A very small single-candidate gene study suggested association of a variant in the ERBB3 promoter region with lung cancer—but only with analysis restricted to a recessive model and limited to a non-smoking subset of 119 cases and 191 controls (P = 0.037)." (PMID 34274969, 2021). "Little is known regarding the implications of the identified variants in lung cancer recurrence, except for ERBB3." (PMID 34599262, 2021). "ERBB3 is considered to play a role in proliferation, differentiation and other normal processes and is associated with cancer cell growth including lung cancer." (PMID 31357969, 2019). "Ectopic expression of ZEB1 in EGFR-mutated lung cancer cells inhibited cell growth by increasing miR-200c target Notch1, which repressed ErbB3 promoter activity and the expression of ErbB3." (PMID 28587302, 2017). "It was reported that ERBB3 played a major role in division, survival, motility, migration, and invasiveness of lung cancer cells and high ERBB3 expression was also associated with poor prognosis in lung cancer patients." (PMID 26988096, 2016). "Here we report that ZEB1 exerts the opposite effect in EGFR-mutated lung cancer cells, where it suppresses growth by increasing microRNA-200 targets to antagonize ERBB3, a driver of mutant EGFR-dependent cell growth." (PMID 27456471, 2016). "RAC1 and ERBB3 have been reported to be associated with drug resistance in lung cancer." (PMID 39338283, 2024). "However, a study finds out that in lung cancer, amplification of c-Met causes gefitinib resistance by driving ERBB3-dependent activation of PI3K, a pathway thought to be specific to EGFR/ERBB family receptors." (PMID 25588551, 2015). "ERBB3 bound EGFR, while we could not identify any ERBB2 peptides, suggesting that EGFR may be the primary partner of ERBB3 in these lung cancer cells with activating EGFR mutations." (PMID 24189400, 2013). "Our findings indicate that the inactivation of NOTCH1 alone, without concomitant inhibition of EGFR, may lead to unexpected outcomes in lung cancer by increasing ERBB3 to promote EGFR-mutated tumour growth, providing a caution against indiscriminate use of NOTCH inhibitors." (PMID 27456471, 2016). "Several monoclonal antibodies (mAbs) against ERBB3 are currently in clinical trials to assess their efficacy in several cancers including lung cancer." (PMID 39695132, 2024). "Evidence is now accruing that EGFR works in concert with other ErbB family members, particularly HER2 and ErbB3, to activate these signaling pathways in lung cancers." (PMID 38091511, 2022). "ARAF is a highly conserved serine/threonine kinase that controls ERBB3 expression in lung cancer, thereby inhibiting AKT activation and subsequently inhibiting tumor metastasis." (PMID 36457486, 2022). "First, MET amplification has been shown to result in constitutive activation of ERBB3 signaling to promote gefitinib resistance in lung cancer cell lines." (PMID 34675407, 2022). "Numerous studies have found that ErbB3 is overexpressed in breast, ovarian, prostate, colon, pancreatic, gastric, urinary, oral, and lung cancers." (PMID 36059813, 2022). "Within NSCLC, ERBB3 expression is higher in adenocarcinoma compared with squamous and other forms of lung cancer; and circulating ERBB3 mRNA levels correlate with higher TNM stage and poorer survival in adenocarcinoma." (PMID 34274969, 2021). "In lung cancers, c‐Met amplification induces gefitinib resistance by regulating the phosphorylation of the epidermal growth factor receptor (ERBB3)/phosphatidylinositol 3‐kinase (PI3K) axis." (PMID 34555268, 2021).
lung cancer (continued). "While upregulation of CEACAM5 and CXCL17 seems to have a biological explanation, the underlying mechanism of the lower systemic levels of both important cancer related receptor tyrosine kinases, VEGFR2 and ERBB3, in lung cancer patients, remains elusive." (PMID 31357969, 2019). "Nevertheless, consideration of both necessary and sufficient part of NICD to transcriptionally attenuate ERBB3 expression by binding to its promoter directly, inhibition of Notch1 inevitably induces ERBB3, a driver of EGFR-mutated lung cancer cell growth." (PMID 31681582, 2019). "At first MET amplification was known to endow ErbB3 signaling with persistent activation and contribute to the resistance to gefitinib in lung cancer cell lines." (PMID 29455669, 2018). "Seribantumab inhibits both basal and HRG-induced phosphorylation of ErbB3 after 1 h or 24 h of treatment in A549 lung carcinoma cells." (PMID 28725482, 2017). "MET amplification has been reported to induce gefitinib resistance via ErbB3 in EGFR mutant lung cancers." (PMID 26919104, 2016). "Although both MET gene amplification and HGF treatment has been shown to induce gefitinib resistance in lung cancers with EGFR mutations, ErbB3 transactivation is involved only in MET amplification but not in HGF-induced resistance." (PMID 26919104, 2016). "Ectopic expression of ERBB3 partially restores growth inhibition induced by GLIPR1, suggesting that GLIPR1 inhibits lung cancer cell growth through suppressing ERBB3." (PMID 26988096, 2016). "GLIPR1 regulates lung cancer growth through the V-Erb-B avian erythroblastic leukemia viral oncogene homolog 3 (ErbB3)." (PMID 26988096, 2016). "Consistently with this conclusion, the RNA-Seq data demonstrated that lung cancer samples express high levels of ErbB2 and ErbB3 or FGFR3." (PMID 27480244, 2016). "In nonsmall cell lung cancer, amplification of MET is associated with resistance to gefitinib, the reversible EGFR tyrosine kinase inhibitor, via ErbB3 activation." (PMID 24500024, 2014). "It specifically downregulates erbB3 and demonstrates significant antitumor activity in mouse xenograft models of breast and lung cancer cell lines." (PMID 24886126, 2014). "The erbB3 signaling also contributes to gefitinib resistance in lung cancer-induced by gene amplification of MET." (PMID 24886126, 2014). "Cell models used included Hep3B, C3A, HepG2 and Huh7, several of which showed an upregulation of erlotinib-resistance genes, AXL, HGF, FGFR1 and ERBB3 in comparison to an erlotinib-sensitive lung cancer line." (PMID 24551227, 2014). "MET amplification in lung cancer has recently been shown to be associated with activation of EGFR, ERBB2, ERBB3, and RET." (PMID 23300999, 2013). "It has been demonstrated in lung cancer that EGFR and c-Met are linked via ERBB3 and this has been implicated in clinical resistance to EGFR TKIs." (PMID 21390244, 2010). "Additionally, elevated ERBB3 expression in LCBM clinical specimens correlated with significantly reduced overall survival and targeted ERBB3 suppressed lung cancer brain metastasis." (PMID 42003929, 2026). "Numerous tumors exhibit aberrant ERBB3 expression, including lung cancer." (PMID 41244106, 2025). "Plenty of studies also pointed out that Afatinib is an irreversible ErbB family blocker, targeting oncogenes such as EGFR, ERBB2 and ERBB3 (that are also included in the oncogene subcomponent of the two cell lines), and is widely used in the treatment of lung cancer." (PMID 37603576, 2023). "Moreover, Axl confers resistance to EGFR-targeted therapy in lung cancer by interacting with ErbB3 and phosphorylation of Akt." (PMID 37746265, 2023). "Despite the apparent effects of HER3 mutations on lung cancer biology, no large-scale clinical trials have been conducted to validate a specific treatment strategy for ERBB3-mutant lung tumors, in contrast to activating EGFR mutations." (PMID 36476337, 2022).